LEF1 (lymphoid enhancer binding factor 1)
Diseases named in the same sentence as LEF1 in open-access papers (continued):
Sharing a sentence is not in itself a finding about the gene and the disease.
osteosarcoma (27 papers, 2015 to 2025). A usually aggressive malignant bone-forming mesenchymal neoplasm, predominantly affecting adolescents and young adults. "This study summarized recent significant advancements, highlighting that METTL3 promotes osteosarcoma cell proliferation by regulating LEF1 m6A methylation and activating the WNT/β-catenin signaling pathway." (PMID 41019082, 2025). "M6A alpha Base transferase METTL3 enhances osteosarcoma progression by increasing m6A methylation of LEF1 mRNA, thereby activating the Wnt/β-catenin signaling pathway and promoting cancer cell proliferation, migration, and invasion." (PMID 39445018, 2024). "Molecularly, RUVBL1 enhances the transcriptional activity of the β-catenin/LEF1 complex by mediating chromatin remodeling at the promoter regions of LEF1 target genes, consequently promoting osteosarcoma metastasis." (PMID 37197432, 2023). "For example, METTL3 can promote the progression of osteosarcoma by regulating the m6A level of LEF1." (PMID 38024481, 2022). "For example, METTL3 regulates SOX2 mRNA in glioma stem cell maintenance and colorectal tumor progression, LEF1 in osteosarcoma progression, AFF4/NF-kB/MYC in bladder cancer, and SPHK2 in gastric cancer." (PMID 36183833, 2022). "The m6A methyltransferase METTL3 promotes osteosarcoma progression by regulating the m6A level of LEF1." (PMID 33490266, 2021). "Up-regulated miR-214-3p promoted proliferation and migration, while suppressed apoptosis of osteosarcoma cells by increasing β-catenin nuclear translocation and LEF1 translation via degradation of DKK3." (PMID 34326690, 2021). "Our results showed that cantharidin up-regulated DKK3, decreased miR-214-3p, p-GSK-3β, active β-catenin, nuclear β-catenin and LEF1 expressions in osteosarcoma cells." (PMID 34326690, 2021). "METTL3 promotes osteosarcoma cell progression by upregulating the m6A level of LEF1 and activating the Wnt/β-catenin signaling pathway." (PMID 33980824, 2021). "This further activate translation of LEF1 in nuclear, resulting in activation of Wnt/β-catenin signaling in 143B cells, thus to promote oncogenesis and metastasis of osteosarcoma." (PMID 34326690, 2021). "METTL3 can promote osteosarcoma development by directly increasing the m6A methylation level and the expression of lymphoid enhancer-binding factor 1(LEF1), and by activating the Wnt/β-catenin signaling pathway." (PMID 34094986, 2021). "The m6A level in total RNA increased in osteosarcoma tissues and cell lines, and METTL3 promoted the cell proliferation, migration and invasion of osteosarcoma by modulating the m6A level of LEF1 and activating Wnt/β‐catenin." (PMID 33029866, 2020). "The levels of Wnt3a, β-catenin and LEF1 in human osteosarcoma cells were significantly higher than those in embryonic osteoblasts." (PMID 33310972, 2020). "METTL3, an m6A methyltransferase, regulates the m6A level LEF1, promoting osteosarcoma progression." (PMID 39924638, 2025). "Moreover, METTL3 can regulate the Wnt/β‐catenin signalling pathway and the m6A levels of LEF1, thus promoting osteosarcoma progression." (PMID 34647424, 2022). "Moreover, METTL3 promotes osteosarcoma cell progression by regulating the m6A level of LEF1 and activating the Wnt/β-catenin signaling pathway." (PMID 33490266, 2021). "This suggests that cantharidin may be a prospective natural drug candidate for osteosarcoma treatment by targeting the miR-214-3p/DKK3/GSK-3β/β-catenin/LEF1 axis." (PMID 34326690, 2021). "In addition, METTL3 promotes osteosarcoma cell progression by regulating the m6A level of LEF1 and activating the Wnt/β-catenin signaling pathway." (PMID 33033522, 2020). "However, the miR-214-3p/DKK3/GSK-3β/β-catenin/LEF1 axis related pharmacological mechanism of cantharidin on osteosarcoma remains unknown." (PMID 34326690, 2021).
osteosarcoma (continued). "CircMYO10 promotes osteosarcoma progression by regulating miR-370-3p/RUVBL1 axis to promote chromatin remodeling and thus enhances the transcriptional activity of β-catenin/LEF1 complex, which indicates that circMYO10 may be a potential therapeutic target for osteosarcoma treatment." (PMID 31665067, 2019). "In summary, this study suggests the miRNAs including miR-22-3p, miR-154-5p, miR-34a-5p, miR-485-3p, miR-93-5p, and miR-9-5p and the genes including LEF1, RUNX2, CSF1R, CDKN1A, and FBN1 are the key factors in the progression of osteosarcoma." (PMID 35340229, 2022). "In conclusion, this study suggested that the miRNAs including miR-22-3p, miR-154-5p, miR-34a-5p, miR-485-3p, miR-93-5p, and miR-9-5p and the genes including LEF1, RUNX2, CSF1R, CDKN1A, and FBN1 act as key factors in the progression of osteosarcoma." (PMID 35340229, 2022). "Then the anti-osteosarcoma effects of cantharidin both in vivo and in vitro, as well as the specific contribution of miR-214-3p/DKK3/GSK-3β/β-catenin/LEF1 axis were further investigated." (PMID 34326690, 2021). "Our previous research showed that FOXO4, IRF8, and LEF1 were differentially expressed (via RNA sequencing) in canine osteosarcoma compared to patient-matched non-tumour tissue." (PMID 38792023, 2024). "Thus, this study suggests that the hub nodes LEF1, RUNX2, CSF1R, VAV3, FZD3, CDKN1A, and FBN1 are key factors in the progression of osteosarcoma." (PMID 35340229, 2022).
lung carcinoma (26 papers, 2013 to 2025). "TCF target genes are closely associated with the prognosis of lung cancer metastasis, and dominant-negative TCFs suppress the brain metastasis of lung cancer cells by regulating LEF1 and the homeobox protein HOXB917." (PMID 26883469, 2016). "Emerging studies have revealed the role of LEF1 in the development of human cancers, including prostate, colon, and lung cancers." (PMID 40933575, 2025). "MiR-34a-5p/miR-34c-5p/miR-302b-3p —LEF1—CCND1/WNT1/MYC axismay be a key mechanism in inhibition of lung cancer metastasis." (PMID 37191432, 2023). "A couple of studies have reported LEF1 overexpression in glioma, lung cancer and oral squamous cell carcinoma." (PMID 36153326, 2022). "In lung cancer cells, increased matrix stiffness triggers activation of lymphoid enhancer binding factor 1 (LEF1) and c-Myb transcription factors and increases discoidin domain receptor tyrosine kinase 2 (DDR2) expression for EMT, invasion, and proliferation." (PMID 35205794, 2022). "Suppressed miR-557 negatively regulates the expression of LEF1 to inhibit the proliferation of lung cancer cells." (PMID 31753039, 2019). "Increased expression of LEF1 in lung cancer cells enhances chemotactic invasion and cell growth." (PMID 39744480, 2025). "RUNX2 and LEF1 are also targeted by miR-196b and miR-557 inhibiting lung cancer metastasis." (PMID 31027181, 2019). "Together, our data showed that two LUAD-specific TFs, MSC and LEF1, might synergize in promotion of lung cancer malignant progression through EMT process." (PMID 29866045, 2018). "In addition, knockdown of LEF1 inhibited migration of lung cancer." (PMID 36101745, 2022). "The other genes AR, ATF2, CUL1, EP300, GATA4, LEF1, SKP2 in these subnetworks have also been identified as important in lung cancer." (PMID 24369052, 2013). "Considering that transcription factor LEF1 is reported to be involved in lung cancer metastasis, and there is a steric hindrance effect that the binding of lncRNA OXCT1-AS1 to the 55 position of LEF1 affects the ubiquitination of LEF1 at the 54 position, we selected LEF1 as a target." (PMID 34337014, 2021). "Studies in A549 lung carcinoma cells showed that inhibiting the expression of DDR2 with siRNA is sufficient to alter activity of the NF-κB and the lymphoid enhancer-binding factor 1 (LEF-1) transcription factors and to inhibit EMT and cell migration induced by TGF-β1." (PMID 27014069, 2016).
hepatocellular carcinoma (22 papers, 2009 to 2025). A malignant tumor that arises from hepatocytes. "For instances, in poorly differentiated hepatocellular carcinoma, LEF1 is frequently overexpressed and strongly associated with poor prognosis and tumor cell differentiation." (PMID 39887653, 2025). "Since the publication of our previous paper, studies targeting β-catenin using a small molecule inhibitor ICG001, or knocking down LEF1, have resulted in the reversal of Lenvatinib resistance in hepatocellular carcinoma cells." (PMID 40566602, 2025). "Overexpression of LEF1 has been frequently observed in primary liver cancer tissues, and it promotes stemness and poor differentiation of hepatocellular carcinoma by directly activating the NOTCH pathway." (PMID 38254216, 2024). "A recent report finds that XBP1s acts on the promoter region of LEF1 to support Wnt signaling in hepatocellular carcinoma." (PMID 39324706, 2024). "For example, by directly activating the NOTCH pathway, LEF1 overexpression promoted poor differentiation and progression of hepatocellular carcinoma." (PMID 34096776, 2021). "Intriguingly, FZD10 and LEF1 were only expressed in the medium-differentiated hepatoma but its para-cancer tissues, while a modest expression level of DVL1 in this hepatoma was examined over that of the para-cancer tissues." (PMID 32273945, 2020). "The role of the Wnt/β-catenin/LEF1 pathway in activation of hepatic cancer stem cells in hepatocellular carcinoma and during liver regeneration has been well characterized." (PMID 29391527, 2018). "LEF1, a major transcription factor of the Wnt pathway, has been reported to play a significant role in cancer progression, such as in T lymphocyte acute lymphoblastic leukemia, hepatocellular carcinoma, and glioma." (PMID 36389690, 2022). "Recent studies have also shown that Lef1 can enhance oncogenic effect in hepatocellular carcinoma (HCC) cells through Notch signalling pathway." (PMID 36243826, 2022). "This aligns with a previous report of lower LEF-1 (and TCF4) levels (protein and mRNA) upon MSI2 depletion in SMMC-7721 hepatocellular carcinoma cells." (PMID 40301545, 2025). "In hepatocellular cancer, WT1‐mediated LEF1 transcription is repressed by mangiferin, which controls β‐catenin‐independent Wnt signaling inactivation." (PMID 39479608, 2024). "Similar observations were retrieved from human hepatocellular carcinoma patients (n = 92), with inverse relation between IRF3 and TCF1/LEF1, and shorter survival time of patients with low IRF3 and high TCF1 and LEF1 expression." (PMID 33188184, 2020). "In human lung adenocarcinoma and hepatocellular carcinoma patients, we also found the level of IRF3 had a strong inverse relation to the expression of TCF1 and LEF1." (PMID 33188184, 2020). "A previous study suggested that LEF1, as a candidate CSC marker, was highly elevated during EMT in hepatocellular carcinoma." (PMID 31296250, 2019). "There is also evidence of a functional link between MTDH and pro-survival mechanisms mediated by the lymphoid enhancer binding factor 1 (LEF-1) and GSK3β components of the Wnt/β-catenin pathway in chronic lymphocytic leukemia and hepatocellular carcinoma." (PMID 31131259, 2019). "The expression of genes encoding proteins known to be associated with the cell cycle (E2F1), adhesion and proteolysis (OPCML) and hepatocellular carcinoma (FZD7, IGFBP1 and LEF1) was elevated 3- to 9-fold." (PMID 26442469, 2015). "Contrary to its canonical role in the Wnt/β‐catenin signaling, LEF1 has been found to directly bind to promoter regions and potentially activate key members of the NOTCH signaling pathway in hepatocellular carcinoma, enhancing self‐renewal capacity, drug resistance, dedifferentiation, and invasion." (PMID 39887653, 2025). "The results revealed a new way of inhibiting hepatocellular cancer through Wnt signaling that was independent of β‐catenin and controlled by WT1‐associated LEF1 suppression." (PMID 39479608, 2024).
hepatocellular carcinoma (continued). "In liver cancer, LEF1 activates both the Wnt/β-catenin and NOTCH signaling pathways, enhancing the tumorigenic capacity of hepatocellular carcinoma (HCC) cells." (PMID 40810004, 2025).
chronic lymphocytic leukemia (21 papers, 2011 to 2025). "Previous studies suggest that down-regulated LEF1 in adult B-precursor acute lymphoblastic leukemia and chronic lymphocytic leukemia (CLL) associated with favorable outcome." (PMID 31929803, 2019). "For example, LEF1 expression has been found to be associated with poor prognosis in adult precursor B-cell acute lymphoblastic leukemia and chronic lymphocytic leukemia, while overexpression of LEF1 has been determined as a favorable prognostic factor in childhood ALL and acute myeloid leukemia." (PMID 32586085, 2020). "It has been found to act as a novel lymphatic enhancer factor/T cell factor (LEF1/TCF)-associated transcriptional repressor and is a putative tumor suppressor in chronic lymphocytic leukemia." (PMID 37894938, 2023). "Previous study indicated that knockdown of LEF1 resulted in TNF-α induced necroptosis in chronic lymphocytic leukemia cells." (PMID 36101745, 2022). "Liu reported that LEF1 is a key regulator of the necroptotic machinery, and knocking it down sensitized chronic lymphocytic leukemia cells to TNFα/zVAD-induced necroptosis." (PMID 36389690, 2022). "The putative targets and functional effectors of miR-26b are the lymphoid enhancer binding factor 1 (LEF1), overexpressed in chronic lymphocytic leukemia and in the monoclonal B cells lymphocytosis, a pre-lymphomatous condition, and cyclooxygenase-2, COX2." (PMID 33260407, 2020). "Expression of WNT3 and LEF1 is amplified in chronic lymphocytic leukemia (CLL) B-cells, a subset of leukemias, compared to normal B-cells." (PMID 33126517, 2020). "Coexpression of CD5, CD23, and LEF1 distinguishes chronic lymphocytic leukaemia from MALT lymphoma, although occasional expression of CD5 or CD23 may be seen in MALT lymphoma." (PMID 40831827, 2025). "Pharmacological suppression of LEF1 by selenite and ethacrynic acid (EA), which inhibit LEF1 transcriptional activity, was also found to attenuate cellular proliferation and promote cellular apoptosis in renal cell carcinoma, chronic lymphocytic leukemia, and multiple myeloma." (PMID 32933177, 2020). "Aberrant activation of lymphoid enhancer-binding factor-1 (LEF1) has been identified in several cancers, including chronic lymphocytic leukemia (CLL)." (PMID 26950276, 2016). "Chronic lymphocytic leukemia (CLL) cells aberrantly express LEF-1 and its expression is required for cellular survival." (PMID 21998751, 2011). "Using a cell-based WNT reporter assay, the diuretic Ethacrynic Acid was identified as a WNT inhibitor by directly interacting with LEF-1 and disrupting the LEF-1/β-catenin complex, thereby leading to the inhibition of chronic lymphocytic leukemia growth." (PMID 39253139, 2024). "In cases of chronic lymphocytic leukemia/small lymphocytic lymphoma (CLL/SLL), LEF1 was continually detected as positive." (PMID 38179383, 2023). "In particular, lymphoid enhancer-binding factor 1 (LEF1), Wnt/β-catenin pathway downstream effector, acts as a suppressor of necroptosis via the transcriptional suppression of CYLD in chronic lymphocytic leukemia." (PMID 36429010, 2022). "A distinction from follicular lymphoma (positive for CD10 and BCL6), mantle cell lymphoma (CD5, cyclin D1, and SOX11), and chronic lymphocytic leukemia (CD5, CD23, and LEF1) is needed." (PMID 35053607, 2022). "In different hematologic malignancies, including lymphomas, chronic lymphocytic leukemia, and ALL and AML, LEF-1 was found to be highly expressed." (PMID 25805670, 2015). "In vitro studies revealed a prosurvival effect of LEF-1 in an AML1-ETO-positive leukemic cell line, primary chronic lymphocytic leukemia cells, and murine T-cell lymphomas." (PMID 25805670, 2015).
lung adenocarcinoma (18 papers, 2013 to 2025). A carcinoma that arises from the lung and is characterized by the presence of malignant glandular epithelial cells. "In human pulmonary arterial endothelial cells (HPAEC), the efficient shRNA-mediated inhibition of FOXF1 decreased LEF1 mRNA but increased growth of spheroids formed by human H-441 lung adenocarcinoma cells and FOXF1-deficient HPAECs." (PMID 38589650, 2024). "LEF1 is able to regulate glioblastoma stem-like cell self-renewal; NFATc2 enhances tumor-initiating phenotypes in lung adenocarcinoma." (PMID 29723215, 2018). "It has been reported that the Wnt/β-catenin target gene LEF1 mediates lung adenocarcinoma metastasis." (PMID 27806330, 2016). "An essential function of the transcription factors LEF1/TCF4 in cerebral metastases of lung adenocarcinomas has been described in mouse models, while their clinical relevance in humans is still unclear." (PMID 23224985, 2013). "An essential function of the transcription factors LEF1/TCF4 in cerebral metastases of lung adenocarcinomas has been described in mouse models, suggesting a WNT/β-catenin effect as potential mechanism." (PMID 23224985, 2013). "In conclusion, this retrospective study underlines the previous results obtained in a mouse model concerning a role of LEF1/TCF4 in brain metastasis of lung adenocarcinoma." (PMID 23224985, 2013). "Taking together the previous results in a mouse model, the defects in embryonic development after LEF1 knock out, and our results, these findings support the importance of LEF1 in a subgroup of lung adenocarcinoma with potential impact on prognosis." (PMID 23224985, 2013). "Notably, the low expression of IRF3 and the high expression of TCF1 and LEF1 were found to be significantly associated with the poor outcome in CRC and lung adenocarcinoma patients." (PMID 33188184, 2020). "Additionally, we revealed the prognostic relevance of a LEF1/TCF4 signature in primary lung adenocarcinomas in a microarray dataset of primary lung adenocarcinomas." (PMID 23224985, 2013). "In addition, LEF1 was found to mediate WNT/TCF Signaling on lung adenocarcinoma metastasis." (PMID 33289586, 2020). "Moreover, one study has indicated that Wnt/β-catenin signaling controls metastatic colonization of target organs and that human lung adenocarcinomas enhance the competence of lung adenocarcinoma cells to colonize bone and brain tissues using distinct Wnt signaling pathways through LEF1 and HOXB9." (PMID 28757546, 2017). "Additionally, the cell-type-dependent effects of β-catenin and LEF1/TCF4 are underlined by our cluster analysis results based on the LEF1/TCF4 signature, in which the revealed clusters depicted diverging enrichment patterns of the cell cycle pathway in the primaries of lung adenocarcinomas." (PMID 23224985, 2013). "Based on the TCGA data, we constructed a lung adenocarcinoma prognosis model, and we found five key Wnt signaling pathway related genes, including AXIN1, CTNNB1, LEF1, FZD2, FZD4." (PMID 36703749, 2022). "LEF1 and HOXB9, two Wnt target genes, are identified as promoters of lung adenocarcinoma metastasis, and WNT/TCF pathway is identified as a determinant of metastasis to bone in lung adenocarcinoma." (PMID 34256750, 2021). "Furthermore, following a bioinformatics approach we generated a LEF1/TCF4 as well as an AXIN2 gene signature in cerebral metastases and investigated their prognostic value in a dataset of primary lung adenocarcinomas." (PMID 23224985, 2013). "Thus, in the present study, we focused on the role of WNT signaling in brain metastases of lung adenocarcinomas, investigating the expression patterns of LEF1, TCF4, and β-catenin in tissue samples of lung adenocarcinoma brain metastases and their impact on patient survival." (PMID 23224985, 2013).